HMGB3 (high mobility group box 3)
Diseases named in the same sentence as HMGB3 in open-access papers (continued):
Sharing a sentence is not in itself a finding about the gene and the disease.
tumor (55 papers, 2013 to 2025). "HMGB3 regulates cell cycle‐associated proteins, impacts cell proliferation, thereby laying the foundation for tumor metastasis." (PMID 41354099, 2025). "Proteomic analyses have identified HMGB3 as a potential prognostic biomarker, with elevated expression linked to DNA repair and tumor progression." (PMID 41194225, 2025). "Recent studies have provided evidence for the strong association between HMGB3 and tumor occurrence, growth and metastasis." (PMID 39390359, 2024). "Through scRNA-seq analysis of the prevalent immune cells and associated tumor cells, their work focused on HMGB3 as a hub gene in the metastatic transition of PDAC." (PMID 36230515, 2022). "Several miRNAs are closely associated with tumor progression by regulating the HMGB3/Wnt-β-catenin pathway axis." (PMID 35912216, 2022). "Taken together, previous findings suggest that HMGB1, HMGB2, and HMGB3 are potential tumor diagnostic and prognostic marker proteins." (PMID 36568211, 2022). "As an X-linked member of the high-mobility group superfamily of HMG proteins, high-mobility group box 3 protein (HMGB3) has been linked with the cell cycle by activating the endogenous cyclin A gene, which promotes tumor growth in gastric cancer." (PMID 34408262, 2021). "HMGB3 is closely associated with tumor occurrence, development, and chemotherapy resistance." (PMID 38529373, 2024). "Recently, it was shown that exosomes with increased levels of miR-200b-3p—derived from hypoxic cancer-associated fibroblasts from the tumor environment, which inhibit the HMGB3/b-catenin/c-Myc axis—can sensitize CRC cells to the chemotherapy drug 5-fluorouracil (thymidylate synthase inhibitor)." (PMID 39062899, 2024). "Additionally, elevated levels of HMGB3 have been linked to the activation of the Wnt/β-Catenin pathway, promoting tumor progression." (PMID 38149239, 2023). "tumor mutations of HMGB3 were mainly distributed in UCEC, SCM, and LUAD." (PMID 35712661, 2022). "Furthermore, it was also found that HMGB3 mutations were favorably related to tumor-associated immune cells through the TIMER2.0 online tool." (PMID 35754798, 2022). "To investigate whether HMGB3-induced angiogenesis and tumour metastasis are linked, we further established tumour xenografts in zebrafish embryos." (PMID 34050127, 2021). "In addition, IHC analysis and immunoblot also demonstrated that HMGB3 knockdown regulated the expression of the tumor-associated proteins in xenografts, resulting in the inhibitions of hTERT and Ki67, and the upregulation of γH2AX." (PMID 33187536, 2020). "Moreover, HMGB3 up-regulation in CRC patients is associated with tumor serosal invasion, lymph metastasis, and TNM classification." (PMID 28678825, 2017). "Furthermore, the NPC-secreted HMGB3 expression was associated with tumour angiogenesis." (PMID 34050127, 2021). "HMGB3 inhibits tumor cell apoptosis by binding to cisplatin‐DNA adducts and activating the nucleotide excision repair pathway." (PMID 41354099, 2025). "In CRC tumor samples, the level of HMGB3 positively correlated with the expression level of LINC00857 but negatively correlated with the expression level of miR-150-5p." (PMID 39062899, 2024). "HMGB3 is highly expressed in many malignant tumors, and it can promote the growth of tumor cells, it can also be used to predict poor prognoses." (PMID 39669558, 2024). "In esophageal squamous cell carcinoma, HMGB3 was predominantly localized in the nucleus of tumor cells as determined by immunohistochemical staining, and partially expressed in the cytoplasm." (PMID 38529373, 2024). "In papillary thyroid cancer (PTC), HMGB3 levels are elevated in both tumor and serum, which correlates with lymph node metastasis and the advanced tumor stage." (PMID 39062899, 2024). "In normal adult cells, the expression level of HMGB3 is relatively low, but it is upregulated in tumor tissues such as breast cancer, non-small cell lung cancer, and glioma." (PMID 38529373, 2024).
tumor (continued). "Both miR-27b and miR-145-5p inhibit the expression of HMGB3 and reduce the viability, proliferation, migration, and invasion of tumor cells." (PMID 39062899, 2024). "The authors showed that binding of miR-142-3p to the 3′ non-coding region (3′UTR) in HMGA1, HMGA2, HMGB1, and HMGB3 mRNAs leads to apoptosis of tumor cells, as well as to decreased proliferation, migration, and invasion." (PMID 39062899, 2024). "HMGB3 binds platinum adducts to DNA, which promotes the initiation of nucleotide excision repair, inhibits tumor cell apoptosis, and stimulates proliferation." (PMID 39062899, 2024). "HMGB3 predominantly accumulates in the nucleus of tumor cells and partially passes into the cytoplasm." (PMID 39062899, 2024). "On the other hand, HMGB3 can participate in tumor development, migration, and proliferation of tumor cells through the WNT/β-catenin signaling pathway." (PMID 39062899, 2024). "HMGB3 is aberrantly expressed in a number of malignancies, contributing to tumor cell progression and predicting poor outcomes." (PMID 37328851, 2023). "Tumor volumes were significantly smaller in mice injected with HMGB3 shRNA cells than in those injected with control pLKO.1 cells." (PMID 37328851, 2023). "High mobility group box 3 (HMGB3)‐containing nuclear exosomes secreted by NPC cells accelerate tumor metastasis by inducing angiogenesis." (PMID 37306659, 2023). "HMGB3 is expressed at low levels in normal adult cells, but is often upregulated in tumor tissues, making it a promising target for therapeutic intervention." (PMID 37328851, 2023). "There was no significant overlap between by Manders’ overlap coefficient, suggesting that HMGB3 is specific to human tumor cell NEPs and that NEPs are distinguishable from NETs." (PMID 36973439, 2023). "Kyoto Encyclopedia of Genes and Genomes pathway analysis of down-regulated genes showed that stem cell pluripotency and the MAPK signaling pathway, which play important roles in tumor progression, are strongly enriched in the HMGB3 knockdown group." (PMID 37328851, 2023). "Taken together, the detection of CEACAM5 and HMGB3 by real-time PCR was suitable for sample prescreening before single-cell or nuclear sequencing experiments requiring the presence of tumor cells." (PMID 36397035, 2022). "In summary, our study suggests that HMGB3 is a hub gene associated with EMT in CTCs, the formation of CTC clusters, and infiltration patterns of immune cells favorable for tumor progression and metastasis to distant organs." (PMID 35754798, 2022). "Analysis of HMGB3 mRNA expression in tumor and normal tissue using the public database Ualcan and GEPIA2." (PMID 35712661, 2022). "In vivo experiments showed that HMGB3 knockdown significantly reduced tumor volume than that in the control (P < 0.01)." (PMID 35912216, 2022). "The abnormal expression of HMGB3 is thought to be correlated with an increased proliferative rate, increased metastatic ability, and poor OS in several tumor types." (PMID 35332131, 2022). "In vivo experiments showed that GLA inhibited EOC tumor growth, meanwhile, upregulated the miR-374b-5p level and downregulated the expression of HMGB3, Wnt3a, and β-catenin in tumor tissues." (PMID 35912216, 2022). "For example, HMGB3 can be regulated by ncRNAs, such as those involved in tumor progression and development." (PMID 35712661, 2022). "According to GEPIA data, the expression of HMGB3 was significantly higher in EOC tumor tissues than that in normal tissues (P < 0.05)." (PMID 35912216, 2022). "In vivo experiments further confirmed that HMGB3 knockdown diminished the tumor volume and reduced the protein level of Ki-67 in mice." (PMID 35912216, 2022). "Among the four candidate genes, CEA cell adhesion molecule 5 (CEACAM5) and high mobility group box 3 (HMGB3) distinguished the tumor from normal tissues and recapitulated tumor cellularity in single-cell transcriptome data." (PMID 36397035, 2022).
tumor (continued). "Based on the IHC results suggesting high expression of HMGB3 in tumor tissues, we also showed strong positive bands in WB, thus confirming the high expression of HMGB3 in CRC tissues." (PMID 35712661, 2022). "The anti-tumor effect of GLA on EOC is closely related to the miR-374b-5p/HMGB3/Wnt-β-catenin pathway axis." (PMID 35912216, 2022). "Based on these results, we recommend sample prescreening using multigene real-time PCR for beta-actin (ACTB), CEACAM5, and HMGB3 to ensure the presence of tumor cells." (PMID 36397035, 2022). "In vivo experiments further validated that GLA inhibits EOC tumor growth via regulating the miR-374b-5p/HMGB3/Wnt-β-catenin pathway axis." (PMID 35912216, 2022). "We analyzed the levels of HMGB3 mRNA expression in all TCGA tumors using the UALCAN database to identify the variation in HMGB3 expression among tumor and nearby healthy tissues." (PMID 36620553, 2022). "In GEPIA2, we further analyzed the expression of HMGB3 in each tumor in detail, and we found that there were 25 tumors in which HMGB3 was highly expressed and three tumors in which HMGB3 was lowly expressed." (PMID 35712661, 2022). "When HMGB3 expression in NB cell lines was inhibited, cell proliferation, migration, and invasion were suppressed, and HMGB3 knockdown inhibited NB tumor development in mice." (PMID 34988076, 2021). "We found that knockdown of HMGB3 did indeed inhibit tumor growth, leading to significantly reduced tumor volume and weight (p < 0.01)." (PMID 34988076, 2021). "To further investigate this finding, we measured the mRNA levels of HMGB3 in tumor and paired healthy tissue." (PMID 33672863, 2021). "Since then, it has been of great interest to study the relationship between HMGB3 and tumour angiogenesis." (PMID 34050127, 2021). "Similar tendencies were observed in a zebrafish/tumour xenograft model, in which HMGB3 expression was significantly correlated with the sprouting of the subintestinal vein." (PMID 34050127, 2021). "Combining these results, we consider that lncRNA-SNHG5 functions as a tumor promoter in NPC by regulating miR-1179/HMGB3 axis." (PMID 32131767, 2020). "Firstly, we found HMGB3 and hTERT were highly expressed in tumor tissues but moderately expressed in the HSIL compared to the normal cervical epithelium." (PMID 33187536, 2020). "Here, upregulation of HMGB3 was identified in NPC and associated with advanced tumor stage in NPC patients." (PMID 32131767, 2020). "In summary, our results show that HMGB3 overexpression is associated with patient with HCC survival, and miR-200b can inhibit tumor progression via directly targeting HMGB3 in HCC." (PMID 30343649, 2018). "qRT-PCR results showed that high expression of HMGB3 had positive correlation with serosal invasion, lymph metastasis, and tumor–node–metastasis (TNM) stage in CRC patient." (PMID 28678825, 2017). "Three groups of patients were identified, those with an intermediate tumor levels of HMGB3 and those with increased or decreased HMGB3 expression in the tumors." (PMID 24098490, 2013). "The mRNA and protein levels of HMGB3 were higher in the tumor compared to adjacent benign specimens and there was an indirect correlation between the expression of HMGB3 mRNA and patient survival." (PMID 24098490, 2013). "HMGB3 was undetected in the normal adjacent tissue samples while abundantly present in the tumor tissue." (PMID 24098490, 2013). "To identify tissue localization, we performed immunohistochemistry staining against HMGB3 protein and found that HMGB3 is localized in the glands and ducts of normal adjacent tissue while widespread in tumor tissue." (PMID 24098490, 2013). "HMGB3 regulates the expression of EMT‐associated transcription factors such as Snail, Slug, and Twist, thereby enhancing the motility and invasive capability of tumor cells." (PMID 41354099, 2025). "As mentioned, tumor cells are characterized by a high level of HMGB3 expression." (PMID 39062899, 2024).
tumor (continued). "In this review, we summarize the currently available data on the molecular structure, post-translational modifications, and biological functions of HMGB3, as well as the possible role of the ubiquitin–proteasome system-dependent HMGB3 degradation in tumor development." (PMID 39062899, 2024). "Moreover, it has been demonstrated that HMGB3 can promote tumor proliferation and migration by activating the Wnt/β-catenin pathway." (PMID 39390359, 2024). "Wnt-mediated suppression of HMGB3 also suppresses tumor cell proliferation." (PMID 39062899, 2024). "Thus, miR-200b-3p (as well as miR-200c-3p) plays a negative regulatory role in relation to HMGB3 and can significantly inhibit tumor development." (PMID 39062899, 2024). "In addition, we demonstrated that HMGB3 promotes tumor growth in a xenograft model via MAPK/ERK signaling." (PMID 37328851, 2023). "In contrast, HMGB3 overexpression dramatically increased tumor volumes and activated MAPK/ERK signaling relative to the control group, whereas administration of the MAPK/ERK signaling pathway inhibitor, AZD6244, or ERK1/2 knockdown, reversed the effect of HMGB3 overexpression." (PMID 37328851, 2023). "They showed that miR-200b-3p can target against zinc finger E-box-binding homeobox 1/2 (ZEB1/2), microfibril-associated glycoprotein 2 (MAGP2), mothers against decapentaplegic homolog 2 (SMAD2) and high mobility group box 3 (HMGB3), thereby inhibiting tumor growth, apoptosis and cellular mobility." (PMID 37705067, 2023). "Of note, HMG family proteins such as HMGB1, HMGB2 and HMGB3 are elevated in human tumor cell NEPs in contrast to S100a4 in mice suggesting that NEP signaling through the RAGE pathway may be conserved between mice and humans." (PMID 36973439, 2023). "Moreover, upon olaparib treatment, the tumor volumes were significantly higher in mice injected with PCMV HMGB3 cells than in those injected with PCMV cells." (PMID 35332131, 2022). "Among them, HMGB3 expression showed the highest correlation with the tumor cell proportion." (PMID 36397035, 2022). "Moreover, after the injection of CAFs-sEV, the expressions of circN4BP2L2 and HMGB3 in tumor tissues were enhanced, while miR-664b-3p expression was reduced, which was reversed after circN4BP2L2 knockdown." (PMID 35722996, 2022). "Next, we assessed whether aberrant HMGB3 expression promoted the tumor response to olaparib treatment in a xenograft mouse model." (PMID 35332131, 2022). "Moreover, we used normal tissues from the GTEx dataset as controls to compare HMGB3 expression in tumor and normal BRCA tissues." (PMID 36620553, 2022). "Therefore, we considered that GLA exerts an anti-tumor effect in EOC by suppressing the HMGB3-regulated Wnt-β-catenin pathway." (PMID 35912216, 2022). "Moreover, tumor-promoting genes such as HMGB3 and IGFBP2 were highly expressed in P01-C2, which implied a poorly differentiated subpopulation of malignant cancer cells." (PMID 35874770, 2022). "Moreover, HMGB3 overexpression partially offset anti-tumor effects of miR-374b-5p overexpression (P < 0.01)." (PMID 35912216, 2022). "In addition to HMGB3-positive cells, Ki-67-positive cells were also decreased in HMGB3 knockdown tumor tissues." (PMID 35912216, 2022). "Moreover, 5-FU significantly downregulated the HMGB3, c-Myc, and β-catenin level in tumor tissues; however, these changes were reversed by CAFs-N/NC-Exo or CAFs-H-Exo." (PMID 36276139, 2022). "Further, the role of HMGB3 in EOC tumor was further confirmed." (PMID 35912216, 2022). "It seems to be promising that the treatment with HMGB3 as an anticancer target could inhibit the survival and metastasis of CTCs and the proliferation of primary tumor cells, which puts forward a new direction for the treatment of PDAC." (PMID 35754798, 2022). "Finally, we analyzed the expression of HMGB3 in tumor tissues and adjacent tissues from the TCGA database." (PMID 35416122, 2022). "HMGB3 promotes tumor development by moderating the Wnt-β-catenin pathway." (PMID 35912216, 2022).
tumor (continued). "Taken together, the key findings of the current study provide evidence demonstrating the promoting mechanism of LINC00319 on cell proliferation, invasion, and self-renewal ability in vitro and tumor growth in vivo in LSCC by increasing HMGB3 expression via recruitment of E2F1." (PMID 34408262, 2021). "Notably, in our tissue samples, a high expression of HMGB3, increased angiogenesis, and patient tumour metastasis were positively correlated." (PMID 34050127, 2021). "CRC tumor tissues showed a significantly higher level of HMGB3 mRNA." (PMID 34753396, 2021). "In vivo, HMGB3 knockdown inhibited NB tumor development in mice." (PMID 34988076, 2021). "To further evaluate the function of HMGB3 in vivo, we determined whether silencing HMGB3 could inhibit tumor xenograft growth in nude mice." (PMID 34988076, 2021). "Here, we explore for the first time the function of nEXO HMGB3 in tumour angiogenesis involved in NPC metastasis using a series of in vitro experiments with NPC cell lines and clinical specimens and in vivo experiments with tumour xenograft zebrafish angiogenesis model." (PMID 34050127, 2021). "Collectively, we confirmed that HMGB3 is involved in tumour angiogenesis." (PMID 34050127, 2021). "Interestingly, previous studies have shown that HMGB3 has binding sites for MIR-20539, which is a microRNA associated with HNSCC, and induces tumour angiogenesis in ovarian cancer." (PMID 34050127, 2021). "Thus, the evidence suggests that HMGB3 plays an oncogenic role in promoting tumor growth in various types of cancers." (PMID 34408262, 2021). "Recent papers have elucidated the tumor‐promoting role of HMGB3 in various ranges of cancers." (PMID 32871048, 2020). "As shown, HMGB3 knockdown effectively suppressed the tumor growth in response to radiotherapy." (PMID 33187536, 2020). "In addition, we further explored the relationship between HMGB3/hTERT expression and clinicopathologic features by means of tumor tissue microarray." (PMID 33187536, 2020). "Moreover, HMGB3/hTERT expression was positively correlated to tumor stage, while negatively corelated with long-term survival." (PMID 33187536, 2020). "In summary, our results indicate that HMGB3 is a tumor promotor, when inhibit, may suppress CRC proliferation and migration." (PMID 28678825, 2017). "Meanwhile, hypoxic CAFs-derived exosomes could reverse 5-FU-induced HMGB3, c-Myc, and β-catenin downregulation in tumor tissues, suggesting that hypoxic CAFs-derived exosomes could reduce the sensitivity of CRC cells to 5-FU via activating HMGB3/β-catenin/c-Myc signaling." (PMID 36276139, 2022). "Thus, miR-664b-3p might serve as a tumor suppressor in the progression of CRC by restraining HMGB3 expression." (PMID 35722996, 2022). "Our informatics analysis and biological experiments suggested that HMGB3 is correlated with the unfavorable clinical outcomes of NB, and plays an important role in promoting cell growth, proliferation, and invasion in NB, potentially representing a new therapeutic target for tumor progression." (PMID 34988076, 2021). "Thus, our data suggested that silencing HMGB3 inhibits tumor growth in vivo." (PMID 34988076, 2021). "In summary, in a zebrafish model, HMGB3 could regulate angiogenesis and promote tumour metastasis." (PMID 34050127, 2021). "HMGB3 activates TGF‐β and Wnt/β‐catenin signaling pathways, thereby enhancing the migration and invasion capabilities of tumor cells." (PMID 41354099, 2025). "Combined with experimental validation, our findings highlight the pivotal role of HMGB3 in ESCC progression and provide a novel theoretical and practical framework for functional tumor classification and individualized treatment strategies." (PMID 40496864, 2025). "Using A549 cell lines, it was shown that knockdown of HMGB3 in NSCLC leads to a decrease in the rate of colony formation and promotes apoptosis of tumor cells." (PMID 39062899, 2024).